TIMP1 (TIMP metallopeptidase inhibitor 1)
Diseases named in the same sentence as TIMP1 in open-access papers (continued):
Sharing a sentence is not in itself a finding about the gene and the disease.
hypothyroid (1 paper, 2025). "This research aimed to compare TIMP-1 levels and LV strain values in euthyroid HT, hypothyroid HT, and healthy control persons." (PMID 40095713, 2025). "While hypothyroid HT patients showed slightly higher TIMP-1 levels in comparison to their euthyroid counterparts, the difference was not statistically significant." (PMID 40095713, 2025).
idiopathic pulmonary arterial hypertension (1 paper, 2021). A sporadic form of pulmonary arterial hypertension (PAH) characterized by elevated pulmonary arterial resistance leading to right heart failure. "Lepetit H's study showed that MMP-TIMPs imbalance (increased TIMP-1 and decreased MMP-3) contributed to smooth muscle cell proliferation in idiopathic pulmonary arterial hypertension." (PMID 35284430, 2021).
IgA nephropathy (1 paper, 2018). "This study, which includes validation through a Western blot analysis, provides the first demonstration of the upregulation of TIMP1 in the urine of Uygur patients with IgA nephropathy." (PMID 30547763, 2018). "We speculated that TIMP1 serves as a positive regulator of ECMs and plays a role in the production and deposition of extracellular proteins in the mesangium during the course of IgA nephropathy." (PMID 30547763, 2018).
IgG4-related disease (1 paper, 2021). "Interestingly, significantly elevated serum concentrations of HA, PIIINP, and TIMP-1, and ELF score, in patients with IgG4-related disease comparing to healthy controls, were previously reported." (PMID 34940542, 2021).
insulinoma (1 paper, 2015). "This is consistent not only with in vitro experiments showing that the addition of TIMP-1 significantly reduces insulinoma cell death, but also with the finding that TIMP-1 prevents cytokine-mediated dysfunction and cytotoxicity in pancreatic islets and β-cells." (PMID 25759846, 2015).
intracranial aneurysm (1 paper, 2015). "In total, there are five MS genes related to intracranial aneurysm (CASP3, ENG, TIMP1, TIMP2, and TIMP3)." (PMID 26486520, 2015).
intraventricular haemorrhage (1 paper, 2026). "The objective of the present study is to examine the association between the presence of various forms of matrix metalloproteinase genes (MMP-1, MMP-9, TIMP-1 and TIMP-2) and their tissue inhibitors, and the incidence of intraventricular haemorrhage (IVH) in premature neonates." (PMID 41898459, 2026).
Jaundice (1 paper, 2018). Yellow pigmentation of the skin due to bilirubin, which in turn is the result of increased bilirubin concentration in the bloodstream. "PDAC is often associated with jaundice, and it was shown that TIMP-1 levels are significantly elevated in patients with PDAC-associated jaundice as well as with jaundice due to non-malignant conditions such as gallstones." (PMID 29394913, 2018). "Here, we determined the possible association of systemic TIMP-1 levels with cachexia and jaundice, two common PDAC-associated conditions." (PMID 29394913, 2018). "It was indeed reported that patients with PDAC-induced jaundice have significantly elevated levels of TIMP-1, compared to PDAC patients without jaundice, and that even benign jaundice can lead to increased TIMP-1 levels." (PMID 29394913, 2018).
juvenile idiopathic arthritis (1 paper, 2019). Juvenile idiopathic arthritis (JIA) is the term used to describe a group of inflammatory articular disorders of unknown cause that begin before the age of 16 and last over 6 weeks. "The aim of this study was to evaluate the concentration of MMP-2, MMP-8, and MMP-9 and their inhibitors TIMP-1 and TIMP-2 of unstimulated whole saliva (UWS) in correlation with the oral health in juvenile idiopathic arthritis (JIA) children." (PMID 31781639, 2019).
kidney tumor (1 paper, 2020). "Based on RNA sequence data from the TCGA database, TIMP1 mRNA expression was compared between kidney tumor samples and adjacent normal tissues." (PMID 32420905, 2020).
larynx cancer (1 paper, 2019). A primary or metastatic malignant neoplasm involving the larynx. "Most studies on the role of MMP-9 and TIMP-1 are related to the evaluation of the expression of these proteins in larynx cancer compared to the controls." (PMID 31143300, 2019).
lentivirus infection (1 paper, 2021). Virus diseases caused by the Lentivirus genus. "In addition, the expression of phosphorylated AKT (Thr 308) was also remarkably decreased after TIMP1 siRNA or miR-618 lentivirus infection." (PMID 34848810, 2021).
male infertility (1 paper, 2019). The inability of the male to effect fertilization of an ovum after a specified period of unprotected intercourse. "The fact that TIMP-1 and 2 levels were decreased in semen of patients with high sperm DNA fragmentation strengthens results that point towards increased inflammatory status in the reproductive system/semen of men with causes for male infertility." (PMID 30696858, 2019).
malignant glioma (1 paper, 2022). A grade III or grade IV glioma arising from the central nervous system. "Further, our finding of a positive and negative association with TIMP1 and TIMP4 expression, respectively, is in line with a previous study comparing their mRNA and protein expression in normal human brain and malignant gliomas." (PMID 35480116, 2022).
malignant mesothelioma (1 paper, 2020). A malignant neoplasm of the pleura or peritoneum, arising from mesothelial cells. "Here we show that Malignant mesothelioma patients have significantly higher level of Galectin-1, Mesothelin, Osteopontin, VEGF, shed SDC-1, MMP-7, HGF, NRG1-β1 and TIMP-1 compared to benign patients." (PMID 32731396, 2020).
malignant pleural mesothelioma (1 paper, 2020). A malignant neoplasm that arises from mesothelial cells in the pleura and shows a diffuse growth pattern. "Taken together, candidate biomarkers (Galectin-1, Mesothelin, Osteopontin, shed SDC-1, VEGF, MMP-7, HGF, TIMP-1 and NRG1-β1) identified in the current study could be diagnostic biomarkers for distinguishing malignant pleural mesothelioma and metastatic adenocarcinoma from benign patients." (PMID 32731396, 2020).
Microcystic Meningioma (1 paper, 2015). A WHO grade I meningioma characterized by the presence of intercellular microcystic spaces that contain mucinous fluid. "The results suggested that the increased ratio of MMP-9 to TIMP-1 might be associated with the formation of microcysts and peritumoral edema in microcystic meningioma." (PMID 25821815, 2015).
middle cerebral artery infarction (1 paper, 2023). Necrosis occurring in the middle cerebral artery distribution system which brings blood to the entire lateral aspects of each cerebral hemisphere. "TIMP-1 levels are associated with an increased risk of death and primary disability after acute ischemic stroke, and serum TIMP-1 levels in patients with middle cerebral artery infarction are inversely correlated with survival rates." (PMID 36959823, 2023).
monocytic leukemia (1 paper, 2013). "It has been previously reported that IL-1β induces both TIMP-1 and MMP-9 in monocytes and monocytic leukemia cells." (PMID 23967215, 2013).
multinodular goiter (1 paper, 2015). Nodular goiter characterized by more than one discrete tissue mass. "Separate analysis of a subset of the multinodular goiter samples with more aggressive PTC subtypes revealed 2 - 4-fold upregulation in the levels of CHEK1, c-MET and TIMP1, and a 2-4-fold downregulation of BCL2, c-KIT, TG and PPARγ (lower part)." (PMID 25868389, 2015).
Multiple Organ Failure (1 paper, 2020). A progressive condition usually characterized by combined failure of several organs such as the lungs, liver, kidney, along with some clotting mechanisms, usually postinjury or postoperative. "The study hypothesis was that the levels of MMP-9 and TIMP-1 were elevated in patients hospitalised in the ICU due to multiple organ failure (MOF) and that the severity of organ dysfunction and treatment outcomes were correlated with the levels of MMP-9 and TIMP-1." (PMID 32190734, 2020).
myasthenia gravis (1 paper, 2022). Myasthenia gravis (MG) is a rare, clinically heterogeneous, autoimmune disorder of the neuromuscular junction characterized by fatigable weakness of voluntary muscles. "We evaluated the plasma levels of MMP-9 and MMP-2 and their tissue inhibitors TIMP-1 and TIMP-2 in a patients’ cohort with generalized myasthenia gravis (MG)." (PMID 36358365, 2022).
myelodysplastic syndrome (1 paper, 2025). A clonal hematopoietic disorder characterized by dysplasia and ineffective hematopoiesis in one or more of the hematopoietic cell lines. "DisGeNET data reveal associations between myelodysplastic syndrome and the genes CD36, DAB2, ENPEP, and TIMP1." (PMID 40565366, 2025).
myeloid leukemia (1 paper, 2023). A clonal proliferation of myeloid cells and their precursors in the bone marrow, peripheral blood, and spleen. "High‐affinity binding of TIMP‐1 to the cell surface of myeloid leukemia cells and keratinocytes has led to the suggestion that TIMP‐1 can signal directly through cell surface receptors." (PMID 37081824, 2023).
Nephrogenic systemic fibrosis (1 paper, 2021). "Nephrogenic systemic fibrosis skin biopsies display increased expression of TIMP-1, but little to no MMP-1." (PMID 35008794, 2021).
oncocytoma (1 paper, 2014). "In the pathological specimens, the mean serum values of MMP-2 and TIMP-1 and -2 were similar in the ccRCC and oncocytoma patients, whereas the value for MMP-9 was 2-fold higher in the ccRCC patients compared with the oncocytoma patients." (PMID 24520285, 2014). "The mean values for MMP-2 and -9 and TIMP-2 in the positive urine specimens were similar in the ccRCC and oncocytoma patients, whereas the mean value of TIMP-1 was higher in the ccRCC patients compared with that of the oncocytoma patients." (PMID 24520285, 2014). "TIMP-1 was detected in all the specimens analyzed; with a mean value of 157±31 ng/ml (range, 120–186 ng/ml) in the oncocytoma patients and 174±78 (range, 63–429 ng/ml) in the ccRCC patients." (PMID 24520285, 2014). "TIMP-1 was detected in two (50%) oncocytoma individuals and in 8/9 (89%) of the ccRCC patients (range, 0.17–55 ng/ml)." (PMID 24520285, 2014). "We observed that TIMP-1 and -2 values were similar in oncocytoma and ccRCC individuals." (PMID 24520285, 2014). "In addition, the mean level of urinary TIMP-1 was higher in the ccRCC patients compared with the oncocytoma patients." (PMID 24520285, 2014). "The mean values of MMP-2 and TIMP-1 were similar in the ccRCC and oncocytoma patients, whereas the mean values of MMP-9 were higher in the ccRCC patients compared with those of oncocytoma patients." (PMID 24520285, 2014).
opisthorchiasis (1 paper, 2022). Infection with flukes of the genus Opisthorchis. "During the progression of chronic opisthorchiasis, the number of Mmp2+, Mmp9+, and TIMP1+ cells in the liver of infected hamsters significantly increased." (PMID 36355906, 2022).
oral submucous fibrosis (1 paper, 2022). "TIMP-1 and -2 have also been proven to be early indicators of oral submucous fibrosis and aging." (PMID 36275775, 2022).
organizing pneumonia (1 paper, 2016). "Gene expression profiling of human and murine organizing pneumonia lesions showed in part comparable expression levels of pivotal genes, notably of TGFB1/Tgfb1, TIMP1/Timp1, TIMP2/Timp2, COL3A1/Col3a1, CXCL12/Cxcl12, MMP2/Mmp2 and IL6/Il6." (PMID 27282780, 2016).
Ovarian cyst (1 paper, 2017). The presence of one or more cysts of the ovary. "Furthermore, significant positive correlations were noticed between the HE4 and MMP-7 (R = 0.24; p = 0.008) or TIMP-1 (R = 0.27; p = 0.002) concentrations as well as between the MMP-7 and TIMP-1 concentrations (R = 0.25; p = 0.006) in the ovarian cysts group." (PMID 28662671, 2017).
pancolitis (1 paper, 2022). Ulcerative colitis that involves the entire colon. "Taking into consideration the extent (E) of the lesions, serum levels of TIMP-1 were also higher in patients with pancolitis; however, the difference was on the verge of statistical significance (p = 0,051, data not shown)." (PMID 35566780, 2022).
Peptic ulcer (1 paper, 2023). The term peptic ulcer refers to acid peptic injury of the digestive tract, resulting in mucosal break reaching the submucosa. "It seems that peptic ulcer disease caused by infection with H. pylori increases the MMP-2/TIMP-1 ratio in patients with peptic ulcers." (PMID 37605137, 2023). "This study aimed to evaluate the ratios of matrix metalloproteinase-2 (MMP-2) to tissue inhibitor of metalloproteinase-1 (TIMP-1) in patients with peptic ulcers that are sensitive or resistant to H. pylori treatment and compare them with healthy individuals." (PMID 37605137, 2023). "In patients with H. pylori-induced peptic ulcers, the MMP-2/TIMP-1 ratio was significantly higher than the healthy controls (P < 0.05)." (PMID 37605137, 2023).
phytosterolemia (1 paper, 2021). "TNFa, TIMP-1, KC/GRO were all significantly elevated for the ABCG5/8 DKO group, consistent with phytosterolemia eliciting an inflammatory response triggering fibroblast activation and fibrosis." (PMID 34465831, 2021).
pituitary tumor (1 paper, 2019). A benign or malignant neoplasm affecting the pituitary gland. "Other authors reported that in addition to the higher mRNA and protein expression levels of MMP-9 found in invasive pituitary tumors, these tumors also showed a decreased expression of TIMP-1." (PMID 31640258, 2019). "Similar observations have been made by other authors, who detected a decreased level of TIMP-1 in conditioned medium derived from pituitary tumors when compared to that from normal pituitary explants." (PMID 31640258, 2019). "More importantly, their work highlights that increased serum levels of MMP-9 and decreased serum levels of TIMP-1 can be quantified in patients bearing invasive pituitary tumors." (PMID 31640258, 2019).
pneumococcal meningitis (1 paper, 2006). An acute purulent infection of the meninges and subarachnoid space caused by Streptococcus pneumoniae, most prevalent in children and adults over the age of 60. "On the protein level, the time course of TIMP-1 concentration within the cortices of rats with pneumococcal meningitis was assessed in a recent study." (PMID 16749930, 2006).
Polypoidal choroidal vasculopathy (1 paper, 2020). The presence of aneurysmal 'polypoidal' lesions in the choroidal vasculature. "A systemic imbalance of MMP-9 and TIMP-1, thought to reflect an imbalance of the extracellular matrix homeostasis, is previously associated with polypoidal choroidal vasculopathy (PCV) in Asian patients." (PMID 32429088, 2020).
Post-kala-azar dermal leishmaniasis (1 paper, 2018). "Some authors suggest that TIMP-1 and TIMP-3 may contribute to pathology in Post-kala-azar dermal leishmaniasis (PKDL) and may inhibit wound healing." (PMID 30572657, 2018).
postmenopausal osteoporosis (1 paper, 2020). Metabolic disorder associated with fractures of the femoral neck, vertebrae, and distal forearm. "Thus the demonstration of MMP-9 and TIMP-1 in serum of female patients with postmenopausal osteoporosis provides information about bone turnover and its changing depending on exercise therapy." (PMID 32071923, 2020). "We reported decreased enzyme activity of MMP-9, as well as increased TIMP-1 in the serum of female patients with postmenopausal osteoporosis, who had been involved in a 12-week exercise program, compared with those who have not got any physical activity treatment." (PMID 32071923, 2020). "During this study, the enzyme activity of serum MMP-9, TIMP-1, as well as MMP-9/TIMP-1 ratio were observed in patients with postmenopausal osteoporosis, before and after prescribing to a 12-week exercise program." (PMID 32071923, 2020). "In our study, we have tried to evaluate the response of enzyme activity of serum MMP-9 and TIMP-1 on appropriate treatment in postmenopausal osteoporosis, which must include pharmacological and nonpharmacological therapy." (PMID 32071923, 2020).
primary aldosteronism (1 paper, 2020). An endocrine disorder characterized by excessive production of aldosterone by the adrenal glands. "Overexpression of Timp-1 is associated with high aldosterone levels in primary aldosteronism patients, who frequently develop fibrosis in the heart and kidneys." (PMID 33391254, 2020).
primary progressive MS (1 paper, 2018). "Another overlapping CPZ/MS gene orthologue, TIMP-1 was also upregulated in the CSF proteome of relapsing versus primary progressive MS." (PMID 30114292, 2018).
primary sclerosing cholangitis (1 paper, 2021). "In a recent multi-centre study including patients with primary sclerosing cholangitis, cilofexor led to a reduction of alkaline phosphatase, ALT, AST and GGT as well as TIMP1 levels and also improved patient-reported outcomes." (PMID 33435509, 2021).
prurigo (1 paper, 2024). A name applied to several itchy skin eruptions of unknown cause. "TIMP-1 regulates matrix metalloproteinases and their inhibitors, and its elevation is associated with lichenification and prurigo in AD." (PMID 38826624, 2024).
psoriatic arthritis (1 paper, 2021). Joint inflammation associated with psoriasis. "Using a panel of eight biomarkers (PIIANP, TIMP-1, ADAMTS-4, CCL2, IP-10 and TGF-β3), this model distinguishes between OA, knee injury and inflammatory knee arthritis (i.e. RA or psoriatic arthritis) with almost 100% efficacy." (PMID 34804052, 2021).
Pulmonary hypoplasia (1 paper, 2013). "SHAM fetuses showed neither real pulmonary hypoplasia nor significant changes in elastin deposition, but sensitive qPCR could detect differences for TNC, TIMP2, and MMP2/TIMP1 ratio." (PMID 23840910, 2013).
radicular cysts (1 paper, 2017). "Previous studies have shown the presence and immunolocalization of MMP-1 and TIMP-1 in human radicular cysts." (PMID 29054963, 2017).
retinal (1 paper, 2021). "The same study also reported a significant correlation between tissue inhibitor metalloproteinase‐1 (TIMP‐1) and retinal detachment height." (PMID 33864341, 2021).
rheumatic heart disease (1 paper, 2014). An autoinflammatory condition following an infection with Group A Beta Hemolytic Streptococcus (GABHS), in which the heart is attacked by antibodies formed in reaction to a recent GABHS infection. "ROC curve analysis demonstrates plasma PICP, total MMP-1 and PIIINP as significant predictors of rheumatic heart disease.PICP performed better than MMP-1, PIIINP or TIMP-1 with AUC of 0.95." (PMID 24603967, 2014).
sarcoidosis (1 paper, 2015). Sarcoidosis is a multisystemic disorder of unknown cause characterized by the formation of immune granulomas in involved organs. "Using real-time PCR, we evaluated the tissue inhibitor of metalloproteinase (TIMP)-1 gene expression by purified AMs of patients with active and inactive sarcoidosis." (PMID 26240517, 2015). "The MMP-9 high levels characterizing AMs from patients with active sarcoidosis paralleled the reduced mRNA amounts of its major inhibitor, TIMP-1." (PMID 26240517, 2015). "Interestingly, we found that AMs from patients with inactive sarcoidosis showed higher TIMP-1 mRNA amounts with respect to AMs from active disease (1.1 ± 0.3 and 2.9 ± 0.9, in inactive and active sarcoidosis, respectively; p < 0.01)." (PMID 26240517, 2015).
serous ovarian tumor (1 paper, 2021). "Based on these findings we focused on quantifying the protein and mRNA expression of TIMP-1, -2 and -3 in the untreated primary serous ovarian tumor samples." (PMID 35047406, 2021).
silicosis (1 paper, 2025). Silicosis is a respiratory disease caused by breathing in (inhaling) silica dust. "In silicosis, MMP9 and TIMP1, its endogenous inhibitors are disrupted to accelerate abnormal deposition of the Extracellular Matrix (ECM)." (PMID 40470053, 2025).
Sjögren’s syndrome (1 paper, 2021). "The increase in MMP-9/TIMP-1 in Sjögren’s syndrome patients’ saliva is strongly involved in destruction of glandular and salivary duct tissues." (PMID 34437596, 2021).